PDPN (podoplanin)
Diseases named in the same sentence as PDPN in open-access papers (continued):
Sharing a sentence is not in itself a finding about the gene and the disease.
cutaneous melanoma (4 papers, 2019 to 2024). A primary melanoma arising from atypical melanocytes in the skin. "PDPN is up-regulated in skin melanoma, which is an aggressive tumor with an increasing incidence, a high degree of malignancy, and high metastatic rate." (PMID 31208371, 2019). "Here we show that there are at least two subsets of lymphatic vessels in cutaneous melanoma, PDPN+LYVE-1+ and PDPN+LYVE-1-, where LYVE-1 is reported in some cases to correlate with the extent of LN metastasis and overall poor prognosis." (PMID 38361951, 2024). "In skin cutaneous melanoma (SKCM), the PDPN expression was negatively correlated with infiltration levels of various immune cells, including CD4 + T cells, CD8 + T cells, M1 macrophage, and NK cells, and positive correlated with M2 macrophage and Treg cells." (PMID 38167452, 2024). "Lymphatic vessel endothelial hyaluronan receptor-1 (LYVE-1), a selective marker of lymphatic vessels, and D2-40, an endothelial marker known as podoplanin, were used to assess LVI in cutaneous melanomas." (PMID 36613587, 2022). "In addition, we investigated the correlation between the expression of PDPN and immune inhibition in SKCM (skin cutaneous melanoma) using the TISIDB database, and found that PDPN was dramatically and positively correlated with immune inhibition." (PMID 38167452, 2024).
dysplasia (4 papers, 2015 to 2023). A usually neoplastic transformation of the cell, associated with altered architectural tissue patterns. "Using the Cox regression method, we observed a HR of 10.238 (95% CI of 2.06–50.889; p = 0.004) for combined dysplasia grade and podoplanin high-score cases compared with cases of low dysplasia grade and with low podoplanin expression." (PMID 35625534, 2022). "Podoplanin expression independently or combined with dysplasia grade could be useful predictive markers of MT in OL." (PMID 35625534, 2022). "In the present study, 60% of patients with dysplasia had positive podoplanin expression." (PMID 26558136, 2015).
epithelial dysplasia (4 papers, 2016 to 2026). "Importantly, both serum and salivary PDPN concentrations increased progressively with increasing epithelial dysplasia severity in patients with OL, supporting the association between PDPN upregulation and malignant transformation risk." (PMID 41594182, 2026). "The reduction of PDPN expression is related to degree of aggression in the epithelium caused by precursor lesions, showing significant difference between low-grade and high-grade intraepithelial neoplasia." (PMID 27313335, 2016). "Although epithelial dysplasia is the gold standard for assessing the risk of oral malignant transformation, podoplanin and adenosine triphosphate (ATP)-binding cassette G2 subfamily protein expression in patients with OLP may be used as biomarkers for risk evaluation." (PMID 36321043, 2022). "Although previous studies have shown that PDPN tissue expression increases with higher grades of epithelial dysplasia, existing evidence is largely limited to immunohistochemical analyses and prognostic evaluation." (PMID 41594182, 2026). "While tissue PDPN expression correlates with the severity of epithelial dysplasia, current research remains largely restricted to immunohistochemical prognostications." (PMID 41594182, 2026). "Importantly, PDPN levels increased progressively with the severity of epithelial dysplasia, supporting its role in oral carcinogenesis and malignant transformation." (PMID 41594182, 2026). "Importantly, both serum and salivary PDPN concentrations increased progressively with increasing epithelial dysplasia severity among patients with OL (one-way ANOVA, p < 0.001)." (PMID 41594182, 2026).
esophageal cancer (4 papers, 2016 to 2017). A primary or metastatic malignant neoplasm involving the esophagus. "Thus, we proposed the algorithm that reflects the change of the basal layer of PDPN + squamous epithelial cells in esophageal cancer and precancerous lesions and the diagnostic recommendations." (PMID 28086225, 2017).
ischemic stroke (4 papers, 2022 to 2025). A stroke disorder caused by obstruction of blood flow to the brain, due to thrombotic (local blood clot formation) or embolic (due to a blood clot or other material traveling from another site) event. "Studies on ischemic stroke have mostly been concerned with the role of PDPN and/or its partner C-type lectin-like receptor-2 (CLEC-2) in acute IS, ischemia–reperfusion injury, and IS outcome." (PMID 37047799, 2023). "In addition, many studies have demonstrated the involvement of PDPN in the pathological processes in the brain, including development, angiogenesis, tumors, ischemic stroke, and other neurological disorders." (PMID 37047799, 2023). "Podoplanin is a small mucin-like glycoprotein involved in several physiological and pathological processes in the brain including development, angiogenesis, tumors, ischemic stroke and other neurological disorders." (PMID 36176432, 2022).
lymphoma (4 papers, 2020 to 2024). A malignant (clonal) proliferation of B- lymphocytes or T- lymphocytes which involves the lymph nodes, bone marrow and/or extranodal sites. "This ability to compensate for the loss of extrinsic cytokine-derived signals is supported by recent data showing that co-culture of DLBCL cells with human lymph node-derived FRC increased their expression of podoplanin, a process linked to lymphoma secreted lymphotoxins and TNF-α." (PMID 33628205, 2020). "Expression of CA9, but not PDPN, is found for several lymphoma cell lines." (PMID 39768175, 2024).
meningioma (4 papers, 2014 to 2025). A generally slow growing tumor attached to the dura mater. "Podoplanin is also expressed in many tumors, including pleural mesotheliomas, lymphangioma, meningiomas, oral and lung squamous cell carcinomas, and head and neck cancers, making it an exciting target for NIR-PIT." (PMID 40430568, 2025). "AQP1, FRZB, PDGFRL, and PECAM1 were consistently underexpressed in meningioma samples; MEDAG, MYC, PAMR1, PDPN and PERP were consistently overexpressed in nearly every meningioma sample by both measurements." (PMID 29073243, 2017). "Besides podoplanin, somatostatin receptors, especially somatostatin receptor 2 (SSTR-2) and somatostatin receptor 5 (SSTR-5), are frequently expressed in meningiomas and are promising targets for malignant meningioma." (PMID 40430568, 2025). "Indeed, human PDPN expression has been observed in 70% of human cutaneous MM, 70–80% of SCC, and 90% of meningioma." (PMID 32380790, 2020).
metastatic carcinoma (4 papers, 2007 to 2023). A carcinoma which has spread from the original site of growth to another anatomic site. "PDPN is frequently upregulated in metastatic cancers to induce RhoA activity and promote cell migration and invasion." (PMID 24618420, 2014). "Podoplanin (PDPN) is a transmembrane sialoglycoprotein highly expressed on metastatic cancer cells." (PMID 28737696, 2017). "Metastatic cancer-1 cells highly expressed mesenchymal markers (e.g., VIM, FN1, and COL1A1), typical of EMT, whereas metastatic cancer-2 cells highly expressed partial EMT (p-EMT) signature genes (e.g., LAMC2, PDPN, and INHBA), indicative of a p-EMT phenotype." (PMID 37853464, 2023). "It is also intriguing that, like Podocalyxin, podoplanin has been proposed to play a functional role in metastatic carcinoma progression by altering polarization rather than by initiating a classical epithelial to mesenchymal transformation." (PMID 17311105, 2007).
papillary thyroid carcinoma (4 papers, 2014 to 2024). "Further studies are needed to fully elucidate complex mechanisms underlying essential differences between papillary thyroid cancer cells with different genetic backgrounds and the role of podoplanin in acquiring metastatic potential." (PMID 30654768, 2019). "We found that PDPN neoexpression is strongly correlated with older (≥45) patients age, which is one of the several classical clinico-pathological high-risk factors in papillary thyroid carcinomas." (PMID 24797369, 2014). "Altogether, our data suggest that PDPN may play an important role in the control of invasion and migration of papillary thyroid carcinoma cells in association with the E/R/M, MMPs and MAPK kinases." (PMID 30654768, 2019). "In order to assess the role of PDPN in the biology of papillary thyroid cancer, we silenced the expression of PDPN in two papillary thyroid cancer cell lines: TPC1 and BcPAP by transfection with targeted siRNA (siPDPN)." (PMID 30654768, 2019). "We had previously shown that PDPN expression contributes to carcinogenesis in the TPC1 papillary thyroid cancer-derived cell line by enhancing cell migration and invasiveness." (PMID 30654768, 2019). "To further assess the role of PDPN in the biology of papillary thyroid cancer, in the current study we assessed the effect of PDPN silencing in these two papillary thyroid cancer cell lines in more detail." (PMID 30654768, 2019). "The observed morphological alterations were supported by the results of Western blot analyses which showed that expression levels of active forms of the E/R/M proteins increased with PDPN overexpression in papillary thyroid carcinoma cells." (PMID 30654768, 2019). "Taken together, these data demonstrate that podoplanin acts as a proinvasive factor in papillary thyroid carcinoma biology." (PMID 24797369, 2014). "Correlation of podoplanin cellular expression with clinical and pathological parameters of human papillary carcinoma of the thyroid." (PMID 24797369, 2014). "We observed that PDPN was solely expressed in the cancer cells of 40% of papillary thyroid carcinoma (PTC) tissues." (PMID 24797369, 2014). "Therefore, we seeked to elucidate the underlying mechanisms of PDPN impact on the E/R/M and EMT pathways in papillary thyroid cancer by analyzing the main actors of these pathways." (PMID 30654768, 2019). "We conclude that PDPN may play an important role in the regulation of invasion and migration of papillary thyroid carcinoma cells by activating E/R/M, MMPs and may also depend on MAPK kinase signaling." (PMID 30654768, 2019). "Previously we have demonstrated that PDPN mediates invasiveness in TPC1 cells derived from papillary thyroid carcinoma (PTC), that may suggest the involvement of PDPN in PTC progression." (PMID 30654768, 2019). "As PDPN was shown to mediate remodeling of the actin cytoskeleton and induce cell migration, we analyzed filamentous actin distribution and cell morphology of papillary thyroid cancer cells 48 h after PDPN silencing." (PMID 30654768, 2019). "Our results demonstrate that PDPN mediates the invasive properties of cells derived from papillary thyroid carcinomas, suggesting that podoplanin might promote PTC progression." (PMID 24797369, 2014). "As PDPN was shown to mediate remodeling of the actin cytoskeleton and filopodia-like formation in addition to induction of cell migration, we examined filamentous actin distribution and cell morphology of papillary thyroid cancer cells 48 h after PDPN silencing." (PMID 30654768, 2019). "The expression of podoplanin (PDPN) has been found in various human cancers, including differentiated thyroid carcinoma." (PMID 30654768, 2019). "An increased expression of PDPN has been observed in papillary thyroid carcinoma (PTC), and it has been suggested that PDPN may be a pro-metastatic factor in PTC." (PMID 35216288, 2022).
papillary thyroid carcinoma (continued). "This suggests that PDPN activity is rather not dependent on the genetic background determining the regulation of these processes in papillary thyroid cancer cells." (PMID 30654768, 2019). "Surprisingly, in contrast to papillary thyroid carcinomas, all of the examined follicular thyroid carcinoma and follicular adenoma cases were negative for PDPN staining." (PMID 24797369, 2014).
pleural mesothelioma (4 papers, 2020 to 2025). A neoplasm that arises from the mesothelial cells of the pleura. "Podoplanin (D2-40): a membranous expression pattern supports mesothelial origin and has highest sensitivity for pleural mesothelioma, showing a membranous staining in 80–100% of PEMs." (PMID 39941848, 2025). "Preclinical studies showed the effectiveness of the podoplanin antibodies and IR700 conjugate in treating pleural mesothelioma and oral cancer." (PMID 40430568, 2025).
acute promyelocytic leukemia (3 papers, 2019 to 2025). An aggressive form of acute myeloid leukemia (AML), characterized by arrest of leukocyte differentiation at the promyelocyte stage, due to a specific chromosomal translocation t(15;17) in myeloid cells. "However, podoplanin is found to be up-regulated in the leukemic promyelocytes of acute promyelocytic leukemia, which causes aberrant platelet binding, activation and aggregation." (PMID 35854240, 2022). "Lavallée and colleagues, using an in vivo xenograft model, found that promyelocytic leukemia cells expressing podoplanin induced thrombocytopenia and prolonged bleeding time, while none of these effects were observed with podoplanin-negative leukemia cells." (PMID 30736372, 2019).
acute respiratory distress syndrome (3 papers, 2019 to 2022). Progressive and life-threatening pulmonary distress in the absence of an underlying pulmonary condition, usually following major trauma or surgery. "Beside its prothrombotic role, CLEC‐2‐podoplanin interaction has also been implicated in acute respiratory distress syndrome (ARDS), sepsis and peritoinitis in mice." (PMID 35435322, 2022).
adenoma (3 papers, 2019 to 2024). A neoplasm arising from the epithelium. "Pericryptal PDPN expression was a diagnostic feature of adenomas and early CRCs." (PMID 39451200, 2024). "On immunohistochemistry, PDPN expression in the lamina propria or stroma of adenomas, early CRCs, and neuroendocrine tumors, their normal neighbors, and non-neoplastic colorectal lesions were compared." (PMID 39451200, 2024). "In contrast, the emergence of PDPN-positive PCFs strongly indicates tumorigenesis, with higher pericryptal PDPN positivity in early AC and adenoma cases supporting this notion." (PMID 39451200, 2024). "All glandular tumor cases (early AC and adenoma) exhibited PDPN expression in the LP, with the majority showing high expression (71/73 in early ACs and 35/39 in adenomas)." (PMID 39451200, 2024). "Early ACs and adenomas have higher pericryptal PDPN expression than their normal adjacent counterparts." (PMID 39451200, 2024). "RCs and some normal adjacent mucosae of ACs and adenomas expressed PDPN, probably because of PDPN induction by humoral factors secreted by tumor cells." (PMID 39451200, 2024). "Many tumor glands (early AC and adenoma) were lined with linear and continuous PDPN-positive cells." (PMID 39451200, 2024). "(Results) Reticular cells or pericryptal fibroblasts in the lamina propria of adenomas and early CRCs showed higher PDPN expression than did normal mucosae and non-neoplastic lesions (p < 0.01)." (PMID 39451200, 2024).
cervical squamous cell carcinoma (3 papers, 2010 to 2017). A squamous cell carcinoma arising from the cervical epithelium. "By contrast, a clinicopathologically conflicting role for podoplanin, namely as a favorable prognostic factor for patients with lung/cervical squamous cell carcinoma (SCC), has recently been reported." (PMID 21034514, 2010).
colon adenocarcinoma (3 papers, 2014 to 2025). "The surface expression of podoplanin on tumour cells induces platelet binding, and a study examining 26 cell lines of the mouse colon adenocarcinoma observed that metastatic clones were associated with higher podoplanin expression and a greater platelet aggregation capacity." (PMID 38106409, 2023). "Intriguingly, co-culture of MSC with the colon adenocarcinoma cell line Caco-2 also led to an increase of PDPN protein expression by MSCs, although to a lesser extent than when MSCs were co-cultured with alternatively activated macrophages." (PMID 40842027, 2025). "Stromal cells pre-conditioned with M2-like macrophages upregulated PDPN and more effectively supported the growth of three colon adenocarcinoma cell lines." (PMID 40842027, 2025). "Functional assays using direct and indirect co-culture systems investigated the influence of macrophage infiltration on stromal PDPN expression and its effect on colon adenocarcinoma cell growth." (PMID 40842027, 2025). "Furthermore, our data show that the reduced growth of colon adenocarcinoma cells was accompanied by decreased nuclear localization of YAP/TAZ when the cells were cultured on PDPN-silenced stromal feeders." (PMID 40842027, 2025). "Our data suggest that counteracting PDPN expression in activated CAFs or treating them with a TGF-β receptor inhibitor or a ROCK inhibitor, reduces their ability to support colon adenocarcinoma cell growth." (PMID 40842027, 2025). "As observed for PDPN gene and protein expression, TGF-β1 induced the most significant changes in stromal feeders supporting colon adenocarcinoma cell growth." (PMID 40842027, 2025). "Mechanistically, high PDPN expression in stromal cells upregulates CAF activation markers, enhances RhoA-mediated cytoskeletal contractility, and promotes ECM protein synthesis, thereby fostering a niche that supports colon adenocarcinoma cell growth." (PMID 40842027, 2025).
colorectal tumors (3 papers, 2024 to 2025). "PDPN expression was significantly elevated in the stroma of the colorectal tumor tissues compared to normal tissues and correlated with M2-like macrophage infiltration." (PMID 40842027, 2025). "PDPN is a small transmembrane mucin-like glycoprotein that was initially characterized as a platelet-aggregation factor in cancer cells from colorectal tumors." (PMID 38410801, 2024).
fibrosis (3 papers, 2018 to 2021). the formation of excess fibrous connective tissue in an organ or tissue in a reparative or reactive process. "OSM augment resulted in the overexpression of FAP and PDPN in OSMR+ stromal cells, which contributed to intestinal fibrosis of IBD patients." (PMID 32332711, 2020).
follicular thyroid carcinoma (3 papers, 2014 to 2023). "PDPN was not detectable in follicular thyroid carcinomas (FTC), follicular adenomas (FA) and normal thyroid tissues." (PMID 29100400, 2017). "In contrast, the follicular carcinoma derived FTC-133 cell line, carrying mutated tumor suppressor gene PTEN, and CGTH-W-1 cell line do not show the PDPN expression." (PMID 24797369, 2014).
germinoma (3 papers, 2021 to 2024). A malignant germ cell tumor arising in the central nervous system. "They found that in 98% of germinomas (including germinomatous components in mixed GCTs), PDPN was diffusely expressed on the surface of germinoma cells." (PMID 39682237, 2024). "The membrane immunoreactivity for C-kit (transmembrane protein with tyrosine kinase activity), CD30 (tumour necrosis factor receptor), and D2-40 (podoplanin) aid in differentiating germinomas from embryonal carcinoma and yolk sac tumours." (PMID 34357128, 2021). "Therefore, PDPN expression may serve as a sensitive immunohistochemical marker for germinoma in CNS GCTs, aiding in diagnosis, monitoring treatment efficacy, and potential antibody-based therapy targeting." (PMID 39682237, 2024).